IL4 (interleukin 4)
Diseases named in the same sentence as IL4 in open-access papers (continued):
Sharing a sentence is not in itself a finding about the gene and the disease.
asthma (continued). "Administration of C. sativus extract with dexamethasone in guinea pigs model of ovalbumin (OVA)-induced asthma increased IFN-γ level, had a stimulatory effect on T-helper 1 cells, and decreased IL-4 production or had an inhibitory effect on T-helper 2 cells leading to improved Th1/Th2 balance." (PMID 38419885, 2024). "We did a preliminary study using eosinophils from patients with asthma and found IL-4, IL-13, or TSLP at concentrations up to 10 nM did not induce eosinophil adhesion, O2− generation, or eosinophil degranulation (data not shown)." (PMID 39624446, 2024). "Additionally, we examined the levels of inflammatory cytokines in sputum and found that IL‐5, IL‐6, IL‐8, TNF‐α, IFN‐γ, CCL17, CCL22, CXCL10, CCL4, CCL2, IL‐4, IL‐13, and CCL26 were significantly lower in stable asthma than in acute asthma." (PMID 39508721, 2024). "Moreover, chitin microparticles also induce viral-specific immunity in respiratory allergy and asthma by increasing IL-12, IFN-λ, and TNF-α and reducing the production of IL-4." (PMID 39203729, 2024). "Note that WSC was more effective than RSC in increasing asthma-related decreased IFN-γ expression and reducing the asthma-related increased IL-4 content at the same dose, but these differences were not significant." (PMID 36717898, 2023). "IL-4 as a cytokine of crucial effector Th2 in allergic asthma can also induce autophagy in B cells dependent on JAK signaling via an mTOR-independent, PtdIns3K-dependent pathway, which can aggravate asthma through multiple mechanisms." (PMID 37063888, 2023). "Eosinophils produce and secrete fibrogenic factors, such as fibroblast growth factor (FGF), heparin binding epidermal growth factor, IL-4, IL-13, IL-17, nerve growth factor, platelet derived growth factor, and transforming growth factor-β (TGF-β), leading to the development of severe asthma." (PMID 36107283, 2023). "Pitrakinra, targeting the α subunit of IL-4R, thereby blocking signaling of IL-4 and IL-13, suffered from similar problems to early mepolizumab trials by testing in unselected asthma populations with no clinical efficacy." (PMID 37265457, 2023). "In the comparison between the PM/OVA and PM groups, OVA affected both the immediate and late reaction of asthma by upregulation of the interleukin-4 (IL-4), FcεRI, eotaxin, and MBP in asthma pathway, and cytokine-cytokine receptor interaction pathway (respectively)." (PMID 36934237, 2023). "Five monoclonal antibodies (mAb) targeting some molecules participating in type 2 (T2) inflammation (i.e., anti-IL4/13, anti-IL-5, anti-IL-5Rα, anti-IgE, anti-thymic stromal lymphopoietin (TSLP)) are now available for severe asthma and some of them are also indicated for CRSwNP." (PMID 37108417, 2023). "Notably, Th2 cell-related cytokines such as IL-4, IL-5, and IL-13 and Th17 cell-related cytokines such as IL-6 and TNF-α increase in patients with asthma." (PMID 37569846, 2023). "In an experimental asthma model using HDM extracts, the airway hyperresponsiveness of TLR9-KO mice improved compared to the WT mice, which was accompanied by a reduction of the mRNA levels of the Th2 cytokines IL-13, IL-5, and IL-4 in the lungs." (PMID 37426425, 2023). "The researchers found that stunted asthmatic children had higher IL-4/IL-10 ratios compared with stunted children without asthma and non-stunted children with asthma." (PMID 37760982, 2023). "Among biologics, dupilumab and tezepelumab target IL-4Rα and TSLP, respectively, and IL-4 and TSLP acted on ILC2s directly in in vivo or in vitro studies; therefore, these biologics might attenuate ILC2-mediated asthma." (PMID 37371472, 2023). "Several cytokines, including interleukin (IL)-4, IL-5, IL-13, IL-25, and IL-33, thymic stromal lymphopoietin (TSLP), and cells such as innate lymphoid cells type 2 (ILC2s), play crucial roles in orchestrating the inflammatory response in asthma." (PMID 37765327, 2023).
asthma (continued). "As well, this circumstance also has been described in asthma patients, where some interleukins have been found raised, such as IL6, IL-4, IL-5, and IL-13, secreted from CD4+ lymphocytes, promoting an allergic inflammation which involves a worse prognosis of asthma disease." (PMID 37920579, 2023). "IL-4 levels were significantly higher in stunted asthmatic children compared with children who were stunted without asthma and non-stunted asthmatic children (p = 0.038)." (PMID 37760982, 2023). "Dupilumab is an IgG4 human monoclonal antibody (mAb) that binds IL-4Ra with subsequent inhibition of IL-4R signaling induced by both IL-4 and IL-13, and down-regulation of TH2 inflammation in a variety of allergic disorders, including atopic dermatitis, asthma, and possibly other allergic diseases." (PMID 36846564, 2023). "The ratio of IL-4/IL-10 levels in stunted asthmatic children tended to be higher than those in stunted children without asthma and non-stunted asthmatic children." (PMID 37760982, 2023). "As a result of increased expression of DPP-4, which is induced by the type 2 cytokines interleukin (IL)-4 and IL-13, in diseases of asthma and type 2 inflammation, such as atopic dermatitis and chronic rhinitis, DPP-4i may help with the management of asthma." (PMID 37025413, 2023). "High serum periostin, TNFα, IL-4, IL-5, and the chitinase-like protein YKL-40 levels, as well as low serum IL-37 levels, were associated with exacerbated asthma in nonsmokers." (PMID 37367073, 2023). "Anti-IL-4 biologic, Pascolizumab, has not achieved better results in clinical trials of asthma and further studies have been discontinued." (PMID 37377958, 2023). "In patients with asthma, CXCL9 levels negatively correlated with IL-4 levels." (PMID 37005469, 2023). "Since our study only covered patients that had been diagnosed before 2015, newer asthma medications that directly target the IL4/IL13/IL4R pathway such as dupilimab are not involved." (PMID 37860183, 2023). "This study found that stunted asthmatic children had higher levels of IL-4 compared with stunted children without asthma and non-stunted asthmatic children (p = 0.038)." (PMID 37760982, 2023). "Conde and co-workers showed that immunizing mice with IL-4 or IL-13 conjugated to a mutant, nontoxic diphtheria toxin elicited persistent neutralizing antibodies that greatly diminished asthma-like symptoms in a mouse model of allergic airway disease." (PMID 36230993, 2022). "Interestingly, opposite to its effects in vitro, dexamethasone was found to counteract the influence of IL-4 and reduce Ym1 expression in the ovalbumin (OVA)-induced asthma model." (PMID 35967383, 2022). "While the isolated blockade of either IL-4 or IL-13 has not been shown to be effective in severe asthma, the dual blockade of IL-4 and IL-13 has been promising." (PMID 35887589, 2022). "After the addition of STAT3 antibody in the co‐culture system of macrophages and naive T cells, the differentiation of Th2 cells decreased and the secretion of IL‐4 also decreased, which indicated that STAT3 may also involved in the immune mechanism of asthma." (PMID 35079347, 2022). "Hasegawa and colleagues have recently shown that serum levels of IL-17A were significantly different between uncontrolled and well-controlled patients, and that IL-17A levels were correlated with levels of IL-4, IL-25, IL-10, and IFN-γ in patients with uncontrolled asthma." (PMID 35546400, 2022). "Furthermore, it was found that the levels of TNF-α, IL-1β, IL-4, IL-5, and IL-13 in the BALF, and the levels of IL-17, IL-6, and OVA-specific IgE were observably increased in serum of RSV-infected asthma mice, while the level of IFN-γ was decreased." (PMID 36213326, 2022).
asthma (continued). "After Pearson correlation analysis, it was revealed that the expression levels of LINC00847 in PBMCs of asthma children were positively correlated with IgE concentration, eosinophil count, IL-4, and IL-17A levels, but negatively correlated with the IFN-γ level of asthma children." (PMID 35356750, 2022). "Similarly, van der Lans showed that anti-IL-4/IL-13 treatment resulted in a complete and enduring remission of EOM, enabling adequate hearing rehabilitation; concurrent control of the comorbid asthma and CRSwNP was obtained." (PMID 35207196, 2022). "Although studies revealed that SMD can attenuate asthma by regulating the expression of inflammatory mediators such as of INF-γ, IL-4, IL-10, IL-13, and TNF-α, the exact mechanism underlying its protective effect remains unclear." (PMID 36578267, 2022). "Nevertheless, when SEB was added, IL-4 production increased again in the PBMCs of CRS-asthma patients, but not in those with CRS or asthma alone or healthy controls." (PMID 35264183, 2022). "It is well-known that IL-4, IL-5, and IL-13 cytokines produced by CD4+ natural killer T cells and CD4+ T MHCII-restricted cells enhance eosinophilia and increase the severity of asthma." (PMID 35733161, 2022). "Moreover, a significant changes of several cytokines related to Th9 cell differentiation in mouse asthma model was detected compared with the control mice group, including forkhead box O1(FOXO1), IL-4, IL-9, IRF4, Spi1, BATF, and IRF1." (PMID 36253857, 2022). "Moreover, dual-positive Th2/Th17 clones secreting copious quantities of IL-4 and IL-17 are present in BALF taken from patients with severe asthma." (PMID 35625801, 2022). "Moreover, SPC treatment improved lung tissue pathology, reduced the cytokine production in BALF (IL-4, IL-5, and IFN-γ), and regulated Th1/Th2 immune imbalance in an asthma model." (PMID 35631330, 2022). "Although 30 mg/kg of CCE exhibited the declines of asthma factors such as inflammatory cell count and IL-5, other factors did not observe the significant difference in IL-4, IL-13, OVA-specific IgE, histological analysis and protein expression." (PMID 36034804, 2022). "In this study, although IL-4 levels were under the detection threshold and IL-13 levels were low in patients with ABPA, their IL-5 levels were significantly higher than those in patients with CPA and were the second-highest after those in patients with asthma." (PMID 35628692, 2022). "For the ABPA group, the IL-4, IL-13 and IFN-γ+ expression on the metacluster all decreased after allergen exposure; however, the expression of these cytokines barely changed in the metacluster of A.f (+) asthma, Treg of ABPA, and A.f (+) asthma." (PMID 35983066, 2022). "The results of the cytokine contents do not agree with the higher levels of IL-4, IL-5 and IL-13 reported in other asthma models." (PMID 35276769, 2022). "Research on the role of IL-27 in asthma has indicated that IL-27 may increase the expression of T-bet mRNA by promoting IFN-γ expression, inhibiting IL-4 synthesis, and enhancing the Th1 response." (PMID 36304255, 2022). "Here, we have comprehensively summarized the current knowledge on how IRS might be possibly involved in the pathogenesis of asthma and BPD, focusing on the signaling pathways of IGF, IL-4, FGF, and TGF- β receptors." (PMID 36077511, 2022). "Parental cognation, serum intracellular cell adhesion molecule-1, and ADAM33 were considerably linked with asthma, although the ABO blood system, IL-4, and serum E-selectin were not." (PMID 36225476, 2022). "In asthma, periostin is recognized as a biomarker of type 2 inflammation and periostin (POSTN) gene expression is up-regulated in bronchial epithelial cells by IL-13 and IL-4." (PMID 36010292, 2022). "In the absence of Cul5, CD4+ T cells became overly sensitive to IL-4 which contributed to asthma pathogenesis." (PMID 35589717, 2022).
asthma (continued). "Notably, latent Chlamydia pneumoniae and Mycoplasma pneumoniae infections have been reported to contribute to the pathogenesis of asthma, showing an increase in IgE, IL-4, IL-5, IL-8, and IFN-γ in asthma." (PMID 36291665, 2022). "Interestingly, we found that most of the cytokines (IL-12p70, IL-13, IL-4, IL-6, TNF-α, and IL-8) in the asthma patients tend to increase when the low expression of eosinophils; but in the ACO group, only INF-γ and IL-10 showed an increase." (PMID 36311545, 2022). "In double IL-4/IL-13 knockout mice, the induction of asthma did not promote tracheal goblet cell hyperplasia and mucin secretion." (PMID 35887041, 2022). "We noticed the significant changes on % of Th17 cells (IL-17), but not on % of Th2 cells (IL-4) in severe asthma." (PMID 36062195, 2022). "In addition, the concentrations of IL-4, IL-5, and IL-13, as well as IL-1β, IL-6, and TNF-α, were greatly elevated in BALF and lung tissues, especially in lung tissues, of asthma mice, which were suppressed after the treatment of Ferr-1 and/or 3-MA." (PMID 35154576, 2022). "And, what is inconsistent with our expectation is that the content of chemokines rather than Th2 cytokines (IL-4, IL-5, IL-13, etc.)surged in the asthma model group, which indicates that the chemokines count for the pathological process of asthma." (PMID 35600943, 2022). "However, in addition to promoting IL-4-dependent activation and proliferation of alveolar macrophages, the anti-inflammatory and protective properties of SP-A may suppress the strong inflammatory responses that are responsible for more severe asthma and fibrosis." (PMID 35444643, 2022). "It was shown that Th2 cytokines, such as IL-4, IL-5, and IL-13, together with eotaxin/CCL11, regulate critical aspects of eosinophil recruitment, allergic inflammation, and airway hyperresponsiveness in asthma." (PMID 33806927, 2021). "More recently, the use of monoclonal antibodies such as anti-IgE, anti-IL-5, anti-IL-5R, and anti-IL-4/IL-13Rα has been demonstrated to be able to control asthma pathogenesis and hence symptoms, but not to resolve the disease." (PMID 34658882, 2021). "Importantly, GRK2 expression within T cells is required for the manifestation of characteristic features of asthma such as AHR, airway inflammation, IgE and Th2 cytokine (IL-4 and IL-13) production, goblet cell hyperplasia and mucus secretion." (PMID 35386975, 2021). "Curcumin downregulated IL-4 and IL-5 levels but upregulated IFN-γ in the BALF of a murine model of asthma and attenuated allergic airway inflammation by modifying the balance of CD4‏+ CD25+ regulatory T cells (Tregs)/T-helper (Th) in ovalbumin (OVA)-sensitized mice dose-dependently." (PMID 34804178, 2021). "Altogether, these results suggest that vaccination with IL-4-K or IL-13-K does not abrogate IL-4 and IL-13 production in this asthma model, but rather induces antibodies that neutralize these cytokines once released." (PMID 33976140, 2021). "Compared to the asthma and COPD groups, higher levels of IL-4, IL-6, TNF-α, IL-1β, IL-17A, and IFN-γ in ACO were observed, and there were significances in IL-4, IL-6, TNF-α, and IFN-γ compared to the control group (P < 0.01)." (PMID 33869177, 2021). "Therefore, the study concludes that IL-4 and STAT6 are potential targets for preventing infection-induced AHR and severity of asthma in future life." (PMID 34226412, 2021). "Despite their common receptor, IL4 and IL13 have non redundant activities in asthma." (PMID 34305924, 2021). "In conclusion, we established an acute model of asthma with AHR, airway inflammation, and increasing levels of IL-4 and IL-5, which could be effectively reduced by the treatment of HL Granule." (PMID 33967801, 2021). "BALB/c mice were used for the model because this mouse strain has inherent robust IL-4 production, i.e., they have a propensity to develop a vigorous type 2 response that resembles many features, although not all, of human asthma." (PMID 34135902, 2021).
asthma (continued). "Th2 cytokines (such as interleukin (IL)-4, IL-5, and IL-13) are produced by CD4+ T cells and are believed to play a key role in asthma pathogenesis by promoting recruitment and activation of mast cells and eosinophils, which are the primary effector cells in the allergic response." (PMID 34356851, 2021). "These asthma therapies have been directed against interleukin 4/interleukin 13, thymic stromal lymphopoietin, CRTH2 antagonists, and the IL-3/5/GM-CSF axis, and bring the possibility of improved asthma control for patients with severe asthma." (PMID 33917396, 2021). "ILC2s do not depend on T cells and secrete a large number of type 2 cytokines (such as IL-4, IL5, IL-9, and IL-13) under the function of IL-25, IL-33 and thymic stromal lymphopoietin (TSLP) to participate in asthma, virus infection and worm-host defense related with the type 2 immune response." (PMID 33514798, 2021). "Meanwhile, Pts treatment could reduce IL‐4, IL‐13, IL‐5, and IgE (total and OVA specific) levels in the asthma model mice." (PMID 34342160, 2021). "The authors also observed increased miR-155 expression in asthmatic sera; however, the absence of correlation with both IL-4 and miR-21 expressions indicated that the effect of both miRNAs on asthma pathogenesis is likely mediated by different pathways." (PMID 33478047, 2021). "Similarly, in a mice model of OVA-induced asthma, the majority of lung-infiltrating γδ T cells express IL-17, while there are scarcely any expressing either IFN-γ or IL-4." (PMID 33661375, 2021). "Dupilumab, a fully human anti–IL-4α receptor monoclonal antibody, inhibits IL-4 and IL-13 and appears to be effective in patients with moderate to severe asthma, regardless of baseline serum eosinophil counts." (PMID 34829866, 2021). "Several lines of evidence support the contention that IL13, and not IL4, controls mucus production in asthma." (PMID 34305924, 2021). "Gene ontology and Kyoto Encyclopedia of Genes and Genomes analyses showed that the differentially expressed genes, HLA-DMB, IL4, HLA-DPB1, and CD40LG, were related to the occurrence of asthma, and HLA-DMB expression was significantly reduced in allergic asthma." (PMID 34714718, 2021). "Other studies have illustrated that deficiency of HIF-1α can reduce eosinophil infiltration, goblet cell hyperplasia, and levels of cytokines IL-4, IL-5, and IL-13 in the lungs of OVA-induced asthma models, further highlighting the importance of the elevated levels of HIF-1α in asthma." (PMID 33980319, 2021). "Furthermore, CXCR4 was reported to decrease airway responsiveness and inflammation by reducing the levels of IL-4, IL-5, and IL-13 in the BALF in OVA-induced asthma." (PMID 34118928, 2021). "Interrupting IL13 in isolation by genetic deletion or antagonistic blockade reversed established mucus secretion, whereas anti-IL4 blockade did not reduce mucin-secreting goblet cells in a murine model of asthma." (PMID 34305924, 2021). "Interestingly, our data indicate that simultaneous administration of IL-2 and IL-4 in vivo suppressed the severity of not only IL-17-dependent EAE, but also several models of murine asthma in both Th1 and Th2-skewed backgrounds." (PMID 33617447, 2021). "mRNA expression levels of IL4, IL5, and IL13 are increased in sputum cells from asthmatic patients in comparison to controls and can be used as molecular biomarkers to categorize patients into T2-high and T2-low asthma endotypes similarly." (PMID 33513844, 2021). "IL-17A and IL4 have a potential synergistic effect with TGF-β1 in inducing bronchial EMT, p-Smad3 expression and ERK1/2 signaling pathway activation, and inhibiting E-cadherin mRNA expression in the setting of severe asthma." (PMID 34069141, 2021). "Finally, progesterone stimulates the production of proinflammatory cells and upregulates the expression of cytokines and proteins such as IL10, IL-1β, IL-5, IL-6, IL-22, IL-4, IL-17A, TNFα, and GATA 3 through the regulation of receptors in asthma." (PMID 35096261, 2021).